UBE3A (ubiquitin protein ligase E3A)
Diseases named in the same sentence as UBE3A in open-access papers (continued):
Sharing a sentence is not in itself a finding about the gene and the disease.
Angelman syndrome (continued). "Angelman syndrome (AS) is a rare neurogenetic disorder due to loss of expression of maternal ubiquitin-protein ligase E3A (UBE3A) gene." (PMID 27626634, 2016). "Another possible cause of reduced EEG delta power in Dup15q syndrome is duplications of UBE3A, the causative gene of Angelman syndrome." (PMID 27977700, 2016). "Angelman Syndrome (AS) is a rare neurodevelopment disorder resulting from deficient expression or function of the maternally inherited allele of UBE3A gene." (PMID 27769316, 2016). "Epigenetic abnormalities in 15q11-13 imprinted region and UBE3A mutation are the two major mechanisms for molecularly confirmed Angelman Syndrome." (PMID 26942024, 2016). "Angelman Syndrome (AS) is a rare neurodevelopmental disorder caused by loss of function of the maternally inherited copy of UBE3A, an imprinted gene expressed biallelically in most tissues, but expressed exclusively from the maternal allele in neurons." (PMID 27146458, 2016). "Mutations or deletions of the maternal allele of UBE3A cause Angelman syndrome (AS), a rare neurodevelopmental disorder characterized by developmental delay, lack of speech, seizures, motor abnormalities, happy affect, and sleep disturbances." (PMID 27306933, 2016). "Angelman syndrome (AS) is a neurological genetic disorder caused by loss of expression of the maternal copy of UBE3A in the brain." (PMID 26727042, 2016). "The symptoms of Angelman syndrome are caused by the absence of functional UBE3A protein in neurons of the brain." (PMID 27484051, 2016). "Since mutations in the catalytic domain of UBE3A are sufficient for development of Angelman syndrome, the lack of ubiquitination and degradation of UBE3A substrates is predicted to increase these substrate protein levels." (PMID 26441497, 2015). "Changes in UBE3A expression levels in neurons can cause neurogenetic disorders ranging from Angelman syndrome (AS) (decreased levels) to autism (increased levels)." (PMID 25948754, 2015). "Directly, HECT-type E3 ubiquitin ligase (UBE3A) dysfunction appears to induce a large spectrum of pediatric cognitive dysfunctions, such as autism and Rett and Angelman syndromes, depending on the mechanism and severity of UBE3A loss." (PMID 26061495, 2015). "Mutations in proteins involved in the UPS have been implicated in neurological disease (e.g., Ube3a in Angelman syndrome and Ube3c in autism spectrum disorders)." (PMID 26314864, 2015). "Loss of UBE3A function is associated with Angelman syndrome which is a developmental disorder that leads to neurological defects in the brain." (PMID 25815718, 2015). "We therefore focussed on the fourth hit UBE3A which encodes an E3 ubiquitin ligase whose mis-regulation has previously been associated with the developmental disorder Angelman syndrome." (PMID 25815718, 2015). "Mutations in the gene encoding Ube3a underlie Angelman’s syndrome, a developmental disorder associated with autism and related disabilities." (PMID 26321915, 2015). "While there are multiple genes in this region, it became apparent that mutations in UBE3A, a paternally-imprinted gene, are sufficient for causing Angelman syndrome." (PMID 26441497, 2015). "Rarely, Angelman syndrome can occur as a result of an isolated mutation on UBE3A; these patients also have sleep disturbances." (PMID 24839550, 2014). "In another animal model of autism (mice deficient for Ube3a, a ligase implicated in Angelman syndrome), OD plasticity following brief MD is severely impaired." (PMID 24987331, 2014). "The gene ubiquitin ligase E3A (UBE3A) is one of the critical genes in the chromosomal 15 region associated with Angelman syndrome." (PMID 24839550, 2014). "In particular, topoisomerase inhibitors have recently been used to reactivate the silenced paternal Ube3a gene, which encodes a ubiquitin E3 ligase, to compensate for the deleted maternal Ube3a in Angelman syndrome (AS)." (PMID 25233079, 2014).
Angelman syndrome (continued). "In Ube3a knockout mice, many features associated with Angelman syndrome are recapitulated, including disturbances of sleep, such as decreased time in REM sleep." (PMID 24839550, 2014). "The remaining known causes of Angelman syndrome involve mutations within UBE3A (~11%), uniparental disomy (~7%), and imprinting defects (~3%)." (PMID 24946931, 2014). "Angelman syndrome (AS) is a debilitating neurological disorder caused by a dysfunctional Ube3A gene." (PMID 23424281, 2013). "Genes involved in ubiquitination pathways have already been implicated in a number of other neurodevelopmental disorders, such as Angelman syndrome (loss of function of maternal copy of UBE3A), and autism (copy number variants in PARK2, RFWD2, FBX040)." (PMID 23356856, 2013). "In most of the Angelman syndrome cases there is deletion in maternal copy of 15q11-13 leading to mutation in UBE3A gene." (PMID 23762344, 2013). "Loss of function of maternal UBE3A causes Angelman syndrome, a neurodevelopmental disorder with intellectual disability, hypotonia and seizures." (PMID 23967326, 2013). "The molecular defects associated with Angelman syndrome (AS) and 15q duplication autism are directly correlated to expression levels of the E3 ubiquitin ligase protein UBE3A." (PMID 23626758, 2013). "Angelman syndrome (AS) is a severe cognitive disorder caused by loss of expression of the maternally inherited allele of the Ube3A ubiquitin ligase gene." (PMID 23424281, 2013). "Angelman syndrome (AS) is a neurodevelopmental disorder associated with genomic imprinting which results from a loss of function of the ubiquitin protein ligase E3A (UBE3A) gene." (PMID 22888453, 2012). "In previous studies, we found oromotor deficits in a Ube3a deficient mouse model of Angelman syndrome and in Fmr1 KO mice." (PMID 22984567, 2012). "Ube3a, a gene that causes Angelman syndrome (AS) when maternally deleted and is associated with autism when maternally duplicated has recently been shown to regulate monoamine synthesis in the Drosophila brain." (PMID 22916201, 2012). "There are several molecular classes of Angelman syndrome including 15q11-q13 deletion, uniparental disomy, imprinting defects and UBE3A gene mutation." (PMID 21235769, 2011). "These last two candidates are the Drosophila homolog of UBE3A, the gene encoding a ubiquitin ligase misregulated in Angelman syndrome, and its target pebble." (PMID 18773074, 2008). "Angelman syndrome (AS) is a neurodevelopmental disorder characterized by cognitive impairment, absent speech, seizures, motor and sleep impairments, and caused by loss of function of the maternal copy of the UBE3A gene." (PMID 41890832, 2026). "Increased expression of UBE3A increases risk of ASD whereas deficiency causes Angelman syndrome." (PMID 41149794, 2025). "Also, there is ample evidence that loss of UBE3A resulted in reduced excitability of layer 5 fast spiking interneurons in the deletion of ubiquitin protein ligase E3A mouse model of Angelman syndrome." (PMID 40652246, 2025). "For example, the UBE3A gene is mostly biallelic expressed, but it is maternal expressed in the brain, and deficiency leads to a complete lack of expression in glutamatergic and GABAergic neurons, also known as Angelman syndrome (see part 4 of this manuscript)." (PMID 39336109, 2024).
Angelman syndrome (continued). "Further, studies show that the inactivation of Ube3a-ATS by CRISPR/Cas9 editing at the level of DNA and RNA result in expression of sense Ube3a in the brain of Angelman syndrome mice by gene therapy approach with adeno-associated virus (AAV) to deliver Cas9 nuclease as well as guide RNA constructs." (PMID 39108836, 2024). "With a high prevalence of comorbid ASD, Angelman syndrome is caused by the deletion of the maternally inherited ubiquitin protein ligase E3A (Ube3a) gene in the 15q11-q13 chromosome region, associated with impaired hippocampus-dependent learning, memory, and emotion." (PMID 38716113, 2024). "Besides viral diseases, mutations in the UBE3A gene cause human diseases, such as a rare neurodevelopmental disorder, Angelman syndrome (AS), and some cases of autism spectrum disorder." (PMID 37541588, 2023). "Maternal loss of the ubiquitin-protein ligase E3A gene (Ube3a) associated with Angelman syndrome produces an excitatory/inhibitory imbalance through neuron type-specific synaptic defects, causing inhibitory deficits from fast-spiking interneurons in the neocortex." (PMID 36693858, 2023). "For example, Angelman syndrome is a rare neurodevelopmental disorder involving severe developmental delay, intellectual disability and seizures, resulting from loss of function of the maternally inherited UBE3A gene on chromosome 15q11–13." (PMID 36192458, 2023). "Moreover, UBE3A interacted with IRF and aggravated IRF-dependent transcription in a UBE3A-deficient Angelman syndrome mouse model." (PMID 37385985, 2023). "Other studies have also found Angelman Syndrome to result from UBE3A gene mutation." (PMID 38248358, 2023). "Angelman syndrome (AS), an autism spectrum disorder, is a neuro-genetic disorder caused by a disruption of the imprinted and maternally expressed Ubiquitin-protein ligase E3A (UBE3A) gene that occurs approximately 1:12,000 live births." (PMID 37891846, 2023). "The leading cause of Angelman Syndrome (AS) is mutations and deletions in UBE3A." (PMID 38248358, 2023). "Errors of paternally expressed genes/transcripts in this region do cause PWS and a second embedded imprinting center controls the maternally expressed UBE3A (ubiquitin-protein ligase E3A) gene causing Angelman syndrome when altered (deleted, mutated or by paternal disomy 15)." (PMID 36901699, 2023). "Interestingly, loss of UBE3A is the causative factor in Angelman’s syndrome, a neurodevelopmental disorder resulting in mental retardation and coordination." (PMID 37461529, 2023). "GABAergic neuron-specific loss of Ube3a was previously shown to cause Angelman syndrome, a rare neurodevelopmental disorder characterized by abnormal electroencephalogram patterns and also enhanced seizure susceptibility, as we also observed in our mammalian phenotype analysis." (PMID 35892672, 2022). "UBE3A isoform 2 is exclusively localized to the cytoplasm, and recent work examining Angelman syndrome–associated missense mutations suggests that cytoplasmic localization of UBE3A at the expense of its nuclear targeting is a predictor of pathogenicity, irrespective of catalytic function." (PMID 36134658, 2022). "Angelman syndrome is a rare neurodevelopmental disorder caused by mutations affecting the chromosomal 15q11-13 region, either by contiguous gene deletions, imprinting defects, uniparental disomy, or mutations in the UBE3A gene itself." (PMID 35637341, 2022). "Angelman syndrome (AS) is a rare genetic neurological disorder caused by loss of the UBE3A protein due to a de novo deletion of the maternally inherited 15q11-q13 region encompassing the UBE3A gene." (PMID 35482908, 2022). "Mean age in years (standard deviation), gender, adaptive behavior skills, Autism Spectrum characteristics, and aggression in children with Angelman syndrome divided by genetic subtype: “deletion” (Class I and II) and “non deletion” (imprinting center defect, UBE3A mutation and uniparental disomy)." (PMID 33664655, 2021).
Angelman syndrome (continued). "Mutations or deletions of the maternally inherited UBE3A gene cause Angelman syndrome." (PMID 33995501, 2021). "A variation of this approach is used for Angelman syndrome (AG), caused by structural variants in the 15q11-13 locus, often leading to complete loss of the UBE3A gene, other LoF mutations in UBE3A or imprinting errors leading to inactivation of the maternal copy of the gene." (PMID 34828273, 2021). "Angelman syndrome (AS) is one of the common genetic disorders that could emerge either from a 15q11–q13 deletion or paternal uniparental disomy (UPD) or imprinting or UBE3A mutations." (PMID 34675349, 2021). "For example, in the case of Angelman syndrome, if MS-MLPA identifies a maternal deletion in the Angelman syndrome critical region, the recurrence risks for the family is ~1%, while if a pathogenic sequence variant in UBE3A is found to be maternally inherited, the recurrence risks will be 50%." (PMID 34071827, 2021). "The abundance and subcellular distribution of UBE3A has been the topic of many previous studies as its dosage and localization has been linked to neurodevelopmental disorders including Autism, Dup15q syndrome, and Angelman syndrome." (PMID 33737669, 2021). "WES could detect a rare variant of Angelman syndrome, identified as the point mutation of the UBE3A gene, which cannot be seen with other modalities." (PMID 34976390, 2021). "Angelman syndrome is thus caused by loss of UBE3A in neurons of the CNS7." (PMID 32066685, 2020). "UBE3A loss of activity results in Angelman syndrome (AS), while its overexpression leads to autism." (PMID 32455880, 2020). "Angelman syndrome (AS) is a neurodevelopmental disorder that is caused by maternal genetic deficiency of a gene that encodes E6-AP ubiquitin-protein ligase (gene symbol UBE3A) mapping to chromosome 15q11-q13." (PMID 31640736, 2019). "Thus, overexpression of SNHG14 and silencing of UBE3A expression were associated with neuronal differentiation in Angelman syndrome model." (PMID 30546117, 2019). "Angelman syndrome (AS) is a neurodevelopmental disorder categorized by severe disability in intellectual functions and affected by the loss of function of maternally inherited UBE3A gene." (PMID 31849603, 2019). "Notably, there are also a few genes (MGRN1, RHOBTB2 and USP8) involved in ubiquitination processes, which UBE3A (the gene responsible for Angelman syndrome) is also linked to." (PMID 31409060, 2019). "As evidence of its involvement in neurodevelopmental disorders, UBE3A is the causative gene of Angelman syndrome, a disorder resulting in the majority of cases from deletion of maternal 15q11.2-q13.1 and characterized by phenotypic overlap with Dup15q syndrome." (PMID 31312421, 2019). "Loss of the maternally inherited UBE3A allele results in Angelman syndrome (AS), a severe neurodevelopmental disorder, which is characterized by severe intellectual disability, motor coordination deficits, absence of speech, abnormal EEG, and behavioral deficits." (PMID 31143434, 2019). "Interestingly, Angelman Syndrome is generally associated with UBE3A deletions, while ASD can be caused by duplications – yet the same individual can be diagnosed with both syndromes." (PMID 31481879, 2019). "The ubiquitin ligase gene Ube3a (also known as E6-associated protein; E6AP) provides an excellent model for studies of gene evolution because of its brain-specific imprinting and implication in the neurodevelopmental disorder Angelman syndrome (AS)." (PMID 28326016, 2017). "Angelman syndrome, most commonly caused by maternal deletion of the 15q11-q13 region, including UBE3A, features enhanced delta oscillations in clinical EEG recordings, suggesting a reciprocal relationship between deletion and duplication of the GABAAR subunits." (PMID 27977700, 2016). "Angelman syndrome is caused by the absence of functional UBE3A protein in the brain." (PMID 27484051, 2016).
Angelman syndrome (continued). "Altered expression of the E3 ubiquitin ligase UBE3A, which is involved in protein degradation through the proteasome-mediated pathway, is associated with neurodevelopmental and behavioral defects observed in Angelman syndrome (AS) and autism." (PMID 27232889, 2016). "Furthermore, the E3 ubiquitin-ligase UBE3A is implicated in both Angelman syndrome and autism spectrum disorders." (PMID 27375430, 2016). "E3 ubiquitin-protein ligase, Ube3a is the only gene within the 15q11-13 duplicated segment consistently expressed solely from the maternal allele in mature neurons, and inactivating mutations or deletions of Ube3a cause Angelman syndrome." (PMID 27458336, 2016). "Besides Angelman syndrome (AS), which is caused by a deficiency of the UBE3A gene in the brain, these Angelman-like syndromes can be derived from chromosomal microdeletion/ microduplication syndromes, or single-gene disorders." (PMID 27864810, 2016). "Angelman syndrome (AS) is a rare neurodevelopment disorder with resulting from deficient expression or function of the maternally inherited allele of UBE3A gene on chromosome 15, which plays an important role in the cellular ubiquitin-proteasome pathway and synaptic development." (PMID 27769316, 2016). "The critical region is the same as PWS (i.e., 15q11-q13), but parental-of-origin is different; either maternal deletion or paternal uniparental disomy causes Angelman syndrome, because the causative gene, ubiquitin protein ligase E3A (UBE3A), is maternally expressed." (PMID 27187441, 2016). "UBE3A mutations are associated with neurological defects in humans with Angelman syndrome." (PMID 25815718, 2015). "Our results suggest that mutated catalytically inactive forms of UBE3A may cause defects in overall proteasome function, which could have an important role in the Angelman syndrome pathology." (PMID 25633294, 2015). "Angelman syndrome-associated UBE3A mutants were kindly provided by Peter Howley." (PMID 25633294, 2015). "UBE3A, a protein from the same family, is associated with both autism and Angelman syndrome." (PMID 25170347, 2014). "VPS13B is indispensable for the Golgi apparatus, and genes important for Golgi morphology and function have been linked to autism disorders, including RAB39B, mutated in a X-linked intellectual disability associated with autism, epilepsy and macrocephaly, and UBE3A, responsible of Angelman syndrome." (PMID 25502226, 2014). "Of note is that UBE3A plays a causal role in a human neuro-genetic disease, Angelman syndrome." (PMID 24728990, 2014). "Interestingly, UBE3A is implicated in the genomic imprinting disorder Angelman syndrome, which shares many features with ASD." (PMID 22949041, 2013). "Thus, in contrast to Angelman syndrome, were hyperactivity is consistently described as a behavioral phenotype, complete or maternal loss of Ube3a expression in mice results in hypoactivity." (PMID 21235769, 2011). "Finally, the ubiquintin protein ligase E3A (UBE3A) can be implicated not only in the pathogenesis of Angelman syndrome but also in the neurodegenerative disorders involving protein aggregation." (PMID 21726470, 2011). "Consequently, Angelman Syndrome patients who naturally have mutations in the UBE3A gene might be at an elevated risk for experiencing more severe forms of COVID-19." (PMID 41141600, 2025). "Our limited knowledge of UBE3A substrates, along with a lack of a comprehensive understanding of the transcriptional networks regulated by UBE3A, leaves the molecular mechanisms underlying seizures and epilepsy in individuals with Dup15q and Angelman syndrome largely unknown." (PMID 40076922, 2025). "For Angelman syndrome, seizure activity may be due to the loss of UBE3A in GABAergic neurons." (PMID 35327449, 2022).